APOE (apolipoprotein E)
Diseases named in the same sentence as APOE in open-access papers (continued):
Sharing a sentence is not in itself a finding about the gene and the disease.
depression (continued). "Although further studies are needed to clarify these mechanisms, these gender differences highlight the complex interplay of DM, depression, and APOE E4 in the context of POAG." (PMID 40778276, 2025). "Further research is required to elucidate the roles of different ApoE isoforms, such as ApoE4 versus ApoE2, in the regulation of GABAergic synaptic function and in the context of depression." (PMID 40530388, 2025). "Behavioral assays demonstrated that ApoE overexpression had a profound impact on the depression-like behaviors of Sus mice." (PMID 40530388, 2025). "Our study demonstrates that ApoE plays a critical role in modulating GABAergic signaling and contributes to the pathophysiology of depression by regulating the expression and function of KCC2." (PMID 40530388, 2025). "After 7 d of intraperitoneal injection treatment with CLP290 (100 mg/kg), behavioral tests demonstrated a significant improvement in depression-like behaviors in ApoE-KD mice." (PMID 40530388, 2025). "The cohort with complete PSQI scores, depression, APOE genotype, and hypothalamic volume was split into two groups based on the median age and analyzed separately (“older”: ≥ 55 years, n = 437; “younger”: < 55 years, n = 420)." (PMID 40356022, 2025). "Our multivariable GLM analysis, adjusted for age and stratified by sex, demonstrated the complex interplay between DM, depression, APOE E4, and AD, underscoring their roles in the pathogenesis of AD." (PMID 40778276, 2025). "DM and depression were all associated with higher CRP, while carrying APOE E4 was associated with lower CRP level in both univariate and multivariate GLM (all p< 0.001) in both female and male population." (PMID 40778276, 2025). "To investigate the role of ApoE in the pathophysiology of depression, we employed the CSDS model, a well-established paradigm for studying depression-like behaviors in rodents." (PMID 40530388, 2025). "To investigate the potential role of ApoE in depression, we performed RNA sequencing (RNA-seq) analysis on hippocampal tissues from both the Ctrl-shRNA and ApoE-KD groups." (PMID 40530388, 2025). "We found that susceptible (Sus) mice exposed to chronic social defeat stress (CSDS) exhibited depression-like behaviors, accompanied by a significant reduction in ApoE and K+–Cl− cotransporter 2 (KCC2) proteins in the hippocampus." (PMID 40530388, 2025). "To further validate the role of ApoE in depression-like behaviors, we employed an AAV-mediated short hairpin RNA (shRNA) strategy on C57BL/6J mice." (PMID 40530388, 2025). "These GWAS investigated specific NPS subdomains, namely psychosis (hallucinations or delusions) and affective symptoms (anxiety, depression, or irritability), and identified three risk loci (ENPP6, SUMF1, and APOE) for psychosis." (PMID 39974048, 2025). "DM and depression were all associated with higher CRP, while carrying APOE E4 was associated with lower CRP levels in both univariable and multivariable GLM (all p< 0.001) in all populations." (PMID 40778276, 2025). "In the present study, we successfully constructed a mouse model of AS co-depression by combining a high-fat diet with bind intervention in ApoE-/- mice." (PMID 40977701, 2025). "For this reason, we evaluated the effect size of Aβ positivity on plasma p-tau217 in the presence of common AD comorbidities (VRF and depression), APOE ε4, body mass index (BMI), and eGFR." (PMID 40725025, 2025). "Future studies should consider investigating the effects of different APOE genotypes on neuropsychological profile and depression in temporal lobe epilepsy." (PMID 39886338, 2024). "The findings from this study reveal significant interactions between sex, APOE ε4 genotype, cognitive performance and depression in individuals with temporal lobe epilepsy." (PMID 39886338, 2024).
depression (continued). "In conclusion, physical exercise interventions do not demonstrate favorable AD-modifying effects, except in women with impaired metabolic health or depression and APOE-ε4 carriers patients with AD." (PMID 38803456, 2024). "Cg‐ApoEtm1UncCdh18Tg(GFAP−APOE i4)1Hol/J) were subjected to stress (lipopolysaccharides, LPS) to elucidate the aetiology of ApoE4‐induced depression." (PMID 38506067, 2024). "Controlling for age, sex, and APOE status, CE showed a positive cross-sectional association with CES-D (depression), and a positive longitudinal association with PSQ (stress)." (PMID 38450380, 2024). "Research, predominantly targeting the apolipoprotein E (APOE) gene, has indicated a potential connection among depression and the APOE e4 genotype." (PMID 39767653, 2024). "Results of a two-way ANOVA examining the effects of sex, APOE genotype, and their interaction on neuropsychological performance and depression." (PMID 39886338, 2024). "This study aims to (i) identify impaired cognitive performance and clinically relevant depression; (ii) explore the interaction between sex and APOE ε4 genotype on cognitive performance and depression in individuals with temporal lobe epilepsy." (PMID 39886338, 2024). "To examine the main effects and interactions of sex and APOE ε4 carrier status on neuropsychological test scores and the Hamilton Depression Rating Scale, we also conducted a two-way Analysis of Variance (ANOVA)." (PMID 39886338, 2024). "LPS treatment induces depression‐like symptoms and dysregulates cytokine expression in ApoE transgenic mice." (PMID 38506067, 2024). "From the ANOVA analysis—performed to explore the main effects and interactions between sex and APOE genotype on cognitive outcomes and depression—emerged significant results that complement the findings from the cut-off comparisons." (PMID 39886338, 2024). "When age, sex, depression, and ApoE genotype were all set as covariates, the QPLEXTM algorithm values showed significant differences among all groups." (PMID 37446296, 2023). "Statistical interactions revealed associations between daytime sleepiness and the following covariates: race and ethnicity, APOE ε4 carrier status, baseline history of cardiovascular disease, and depression." (PMID 37457508, 2023). "Carrying the ε3/ε4 genotype of the APOE gene more than doubled the odds of developing major depression compared to carriers of the ε3/ε3 genotype." (PMID 37763074, 2023). "Associations were independent of age, clinical confounders, menopause type, hormone therapy status, history of depression, APOE-4 status, and regional effects of estradiol." (PMID 38774256, 2023). "Carrying the ε3/ε4 genotype of the APOE gene increased the odds of developing high levels of depression by 2.167 (95% CI 1.100–4.266) times compared to the carrier of the ε3/ε3 genotype of the APOE gene (χ2 = 5.120 df = 1 p = 0.024)." (PMID 37763074, 2023). "When age, sex, depression, and ApoE genotype were set as covariates simultaneously, there were significant differences between all clinical groups." (PMID 37446296, 2023). "In elderly, a combination of 1,491 mg DHA and 351 mg EPA per day was effective in modulating the function of APOE ɛ4 carriers on depression and anxiety scores." (PMID 37485386, 2023). "Results were independent of age, menopause type, hormone therapy status, history of depression, and APOE-4 status." (PMID 38774256, 2023). "MCI Model 2 included ADAS11, MMSE, RAVLT, LM-DR, FAQ, History of Depression, APOE ε4 status, hippocampus volume and whole brain volume as variables." (PMID 37904154, 2023). "In summary, ApoE−/− mice showed increased depression and anxiety behavior in comparison with ApoE−/− mice fed only with a high-fat diet under the action of binding stimulation." (PMID 35558553, 2022). "Within the full sample, controlling for pathological status, age, gender, depression, anxiety and CDR-SOB status, APOE-ε4 homozygosity was associated with sleep disturbance (β 2.53, p=0.034)." (PMID 35354468, 2022).
depression (continued). "In our study population, APOE ε4 allele was also associated with GDS (p = 0.037), the test evaluating depression." (PMID 39081475, 2022). "Although we found no direct effect of hsa-miR-107 on verbal memory, we were able to identify a biological signal for the interaction between APOE ε4 status and depression that shows a remarkable connection to the Aβ system and the progression of AD." (PMID 35884866, 2022). "In humans, three major apolipoprotein E isoforms (APOE2, APOE3, and APOE4) have been documented and extensive epidemiological and genetic screening has revealed a possible association between apolipoprotein E (APOE) polymorphism and depression." (PMID 34611141, 2021). "The current study aimed to add to the few longitudinal population-based studies of the role of APOE in later-life depression and to extend previous study using a large, well-phenotyped birth cohort." (PMID 33648619, 2021). "Baseline HDRS values for depression were significantly different between APOE-2/3 and 3/4 (p < 0.05) and 2/3 vs. 4/4 (p < 0.05); and also between APOE-2/4 and 4/4 (p < 0.05) and between APOE-3/3 and 4/4 (p < 0.05)." (PMID 33920985, 2021). "The current study represents one of the first attempts to examine the role of APOE in later-life depression longitudinally among a single-year birth cohort." (PMID 33648619, 2021). "APOE plays an important role in many diseases, including neurodegenerative diseases such as depression, dementia with Lewy bodies (DLB), Parkinson's disease (PD), and multiple sclerosis (MS)." (PMID 34733192, 2021). "Participants who did not have MMSE data at the first follow-up were on average older, more often APOE ɛ 4 carriers, and had more often depression or chronic diseases." (PMID 32110803, 2020). "Comparable synergistic results with APOE were observed for depression, anxiety, apathy, appetite, or irritability, either under the influence of adjustment variables or without them." (PMID 33208795, 2020). "Although protective effects of ApoE ε2 have been reported in MDD, and ApoE ε4 may be associated with late-onset depression, the conclusions of previous studies were not in complete agreement." (PMID 32795354, 2020). "Previous studies have reached different conclusions regarding an association between apolipoprotein E (APOE) polymorphisms and depression." (PMID 30834074, 2019). "It shown depression patients carrying APOE ε4 genotype got higher HAMD score, the difference was statistically significant (OR=0.96, 95%CI=0.16-1.76, P=0.02)." (PMID 30834074, 2019). "We have found the majority of δ’s variance to be associated with a large number of pro- and anti-inflammatory serum protein biomarkers, independently of age, depression and APOE." (PMID 28291794, 2017). "On average, the groups were similar in terms of years of education, literacy, APOE-ε4 status, family history status and depression scores." (PMID 29375365, 2017). "Collectively, clinical studies have pointed toward a possible complex interaction of ApoE, AD, and depression." (PMID 28934977, 2017). "The results of these analyses provide strong evidence that ERβ agonism potently interacts with ApoE isoforms in modulating the brain mechanisms involved in depression." (PMID 28934977, 2017). "Taken together, these data indicate that CUMS treatment successfully induces depression-like behaviors in ApoE-TR mice." (PMID 27406263, 2016). "In Age, depression and APOE adjusted models, we have found the majority of δ's remaining variance to be associated with a large number of pro- and anti-inflammatory serum protein biomarkers." (PMID 27922822, 2016). "In the present study, we created a depression model by treating 3-month-old ApoE-TR mice with chronic unpredictable mild stress (CUMS)." (PMID 27406263, 2016). "The combination of APOE and ACE polymorphic variants in bigenic clusters yielded different anxiety and depression patterns at baseline and after one year of treatment." (PMID 22482072, 2012).
depression (continued). "At baseline, all APOE variants show similar anxiety and depression rates, except the APOE-4/4 carriers who differed from the rest in significantly lower rates of anxiety and depression." (PMID 22482072, 2012). "Concerning depression, all APOE genotypes improved their depressive symptoms with treatment except those with the APOE-4/4 genotype, which worsen along the treatment period." (PMID 22482072, 2012). "ApoE may be involved in the pathophysiology of depression by regulating KCC2-mediated GABAergic synaptic function." (PMID 40530388, 2025). "In this study, we sought to elucidate the role of ApoE in the pathophysiology of depression." (PMID 40530388, 2025). "CMP induces systemic inflammation, oxidative stress, and behavioral changes (e.g., physically inactive, depression), which could interact with APOE ɛ4-related pathways to accelerate cognitive decline." (PMID 40101131, 2025). "However, a decrease in systolic blood pressure was observed in the supplement group, and a significant interaction was found between DHA supplementation and APOE ɛ4 carrier status, indicating improvements in depression and anxiety scores among carriers." (PMID 40918179, 2025). "Next, we investigated the impact of CLP290 on depression-like behaviors in ApoE-KD mice." (PMID 40530388, 2025). "Notably, overexpression of ApoE in the hippocampus significantly ameliorated the depression-like behaviors in Sus mice." (PMID 40530388, 2025). "Being female, having DM and experiencing depression were all associated with higher CRP, while carrying APOE E4 was associated with lower CRP in both univariate and multivariate GLM (all p< 0.001) in all populations (all participants with/without DM and DM patients with/without DR or depression)." (PMID 40778276, 2025). "The associations observed between the APOE ε2 allele and verbal memory performance were confirmed in the subgroup of participants without depressive symptoms (GDS > 5, N = 303), thus ruling out potential confounding effects due to depression." (PMID 41226628, 2025). "In the context of psychiatric disorders (such as depression, schizophrenia), APOE may also influence disease development and progression by regulating immune responses and inflammation." (PMID 39975850, 2025). "Together, these findings suggest that the reduction in ApoE from hippocampal astrocytes may contribute to CSDS-induced depression-like behaviors." (PMID 40530388, 2025). "In fact, they found that children carrying the APOE e4 allele who had higher mercury levels in their cord blood had increased indicators of behavioral deficits, as measured by the Child Behavior Checklist (CBCL), including symptoms of anxiety and depression." (PMID 39803412, 2025). "It has been suggested that the effects of PA on AD pathology could be sub-group specific: PA might be more beneficial in women with metabolic disease or depression or in APOE ε4 carriers." (PMID 40082178, 2025). "Furthermore, disclosing the APOE genotype after careful and sufficient information distribution does not always result in adverse consequences (e.g., increased anxiety or depression levels) in clinical research settings." (PMID 38225507, 2024). "A meta-analysis among non-AD populations demonstrated that the presence of the APOE e4 allele was related to a higher risk of late-life depression." (PMID 38473892, 2024). "In addition to neurodegenerative phenotypes, we also compared APOE gene expression between neuropsychiatric diseases (schizophrenia, bipolar disorders [BP], major depression disorders [MDD]), and controls in LIBD European and African individuals." (PMID 39210471, 2024). "A comparison of plasma protein expression between patients with depression and healthy controls has revealed that differentially expressed proteins, including apolipoproteins such as the APOE, APOC4, and APOA5, lead to significant alterations of lipid and metabolic functions." (PMID 39062058, 2024).
depression (continued). "In addition, we compared the presence of depression between males and females taking into account the APOE genotype." (PMID 39886338, 2024). "In addition, further evidence is needed regarding the relationship between the APOE genotype and specific subdomains of affective dysregulation, including depression, anxiety, and elation." (PMID 38473892, 2024). "Hence, it is possible that exercise still has an effect on specific populations that display risks factors for AD such as women, APOE-ε4 genotype carriers, individuals with metabolic disorders or depression." (PMID 38803456, 2024). "In addition, all the significant interactions remained unchanged after further adjusting for interactions between sex and APOE genotype, depression, or self-reported symptoms of possible sleep apnea, and they survived correction for multiple comparisons." (PMID 39736697, 2024). "The distribution of age, sex, depression, and ApoE genotype differed for each clinical group." (PMID 37446296, 2023). "We also performed ANCOVA to adjust for covariates, such as age, sex, depression, and ApoE genotype." (PMID 37446296, 2023). "Neither APOE ε4 nor any of the biomarkers were statistically significantly associated with incident depression." (PMID 37951931, 2023). "Finally, we analyzed the relationship between our algorithm values and the subgroups fractionalized by some factors known to influence the onset of AD, such as sex, age, depression, or apolipoprotein E (ApoE) genotype." (PMID 37446296, 2023). "In terms of mood and cognition, APOE ɛ4 carriers have been found to have a higher risk for developing depression and anxiety compared to non-carriers." (PMID 37485386, 2023). "However, to fully understand these interactions, further investigation into the role of APOE ε4, depression, physical activity, and cognition in the context of PD is warranted." (PMID 38026513, 2023). "The presence of APOE ε4 allele is associated with hyperhidrosis and depression, but not global cognition, activitives of daily life, motor function and other neuropsychitric symptoms in DLB." (PMID 36123648, 2022). "Full multivariate linear regression revealed a statistically significant effect of APOE ε4 homozygosity on global scores of sleep disturbance (β 2.53, p=0.034) controlling for AD pathological status, ε2 carrier status, age, gender, depression, anxiety and CDR-SOB status." (PMID 35354468, 2022). "They showed little psychological impact of APOE disclosure on depression, anxiety, and stress, with limitations due to exclusion of individuals with clinically significant anxiety and depression, high prevalence of female and well-educated individuals, and relatively short follow-up (1-year)." (PMID 36551936, 2022). "Results were stratified for sex, depression, and Apolipoprotein E4 (ApoE4)." (PMID 36105871, 2022). "Note, however, that depressive symptom scores increased slightly over the study period, and that presence of the APOE e4 allele did not predict death as a competing risk (HADS-Depression cut-off: p = 0.140; medication cut-off: p = 0.520)." (PMID 33648619, 2021). "APOE was also not identified as a predictor of depression in two recent genome-wide association studies." (PMID 33648619, 2021). "However, there is growing evidence that APOE e4 is particularly important for later-life depression." (PMID 33648619, 2021). "One of the cross-sectional studies from the MCSA has demonstrated an association between glucose hypometabolism on FDG-PET and depression measured on the NPI-Q (OR = 2.12; 95%CI, 1.23–3.64; P ≤ 0.05), especially in apolipoprotein E4 (ApoE4) carriers (OR = 2.59; 95%CI, 1.00–6.69; P = 0.05)." (PMID 33789730, 2021). "However, due to limited sample size, wide disparities in study designs and procedures, there are approximately as many studies of APOE ε4 and depression that report positive results as those that find null results." (PMID 34611141, 2021).